EPO (erythropoietin)
Diseases named in the same sentence as EPO in open-access papers (continued):
Sharing a sentence is not in itself a finding about the gene and the disease.
iron deficiency (continued). "The measured HbA1c value of patients with diabetes and HD may be lower than the actual value due to many factors, such as shortened life span of red blood cells, blood transfusion, use of iron and erythropoietin, while the measured HbA1c value is higher when there is iron deficiency or VitB12." (PMID 39628691, 2024). "In addition to iron deficiency and inflammation, EPO is shown to increase FGF23 production." (PMID 36831276, 2023). "Increased iron consumption because of increased serum EPO production by the allograft, and blood loss (transplant surgery, repeated sampling, use of anticoagulants, return of the menstrual cycle, and malignancies) may cause an absolute iron deficiency." (PMID 37415623, 2023). "Iron deficiency may also adversely affect erythropoiesis, as indicated by in vitro studies where in iron deprivation inhibited the maturation of early erythroid progenitors by loss of their response to the hormone EPO." (PMID 34440444, 2021). "In the Correction of Hemoglobin and Outcomes in Renal Insufficiency (CHOIR) trial, the highest risk of cardiovascular death was seen in patients with the highest EPO dose, suggesting that EPO resistance through inflammation and/or functional iron deficiency might be a possible link." (PMID 32512806, 2020). "Notably, several stimuli couple increased FGF23 transcription with increased post-translational cleavage, including inflammation, iron deficiency, erythropoietin, and parathyroid hormone, resulting in elevated concentrations of circulating total FGF23 but not intact FGF23." (PMID 31487315, 2019). "Notably, we identified FGF23 as a potential mediator of iron-deficiency–and EPO-related mortality." (PMID 31170159, 2019). "Finally, although we have strong evidence from the literature that FGF23 is a mediator in the association of iron deficiency and EPO with mortality, we cannot exclude that an unmeasured cause of mortality or alternative potential mediators have influenced the current results." (PMID 31170159, 2019). "However, this is followed by a reduction in blood iron, transferrin levels, and saturation and an increase in erythropoietin levels in the recovery period (3 or 15 days after race), consistent with the reported acute iron deficiency in marathon runners during this time period." (PMID 31244673, 2019). "Besides the well recognized erythropoietin and iron deficiencies, hydration status might be involved." (PMID 30894885, 2018). "In multivariate analysis, absolute iron deficiency was associated with lower hepcidin values, and inflammation combined with a normal or functional iron profile with higher values, independent of other determinants of hepcidin concentration, including EPO, mGFR, and albuminemia." (PMID 24978810, 2014). "In addition, experimental animal models with severe iron deficiency have major disruption in energy production causing cardiac damage, with diastolic dysfunction and heart failure, accompanied by reduced EPO and increased TNF-α serum levels and worsening of molecular signaling pathways." (PMID 22536520, 2012). "Inflammation-driven functional iron deficiency (FID), inadequate EPO production, and disrupted iron homeostasis are central mechanisms that contribute to impaired erythropoiesis in this population." (PMID 41282024, 2025). "Iron deficiency context: Inhibits all three HIF-PHD isoforms, stabilizes HIF-1α/2α, and maintains ↑ EPO despite cytokines." (PMID 41020856, 2025). "Iron deficiency and dysregulation are common in CKD due to reduced erythropoietin production and chronic inflammation." (PMID 40002748, 2025). "The causes of renal anemia include erythropoietin (EPO) deficiency, iron deficiency, disorder of iron metabolism in the body, and resistance to the EPO signaling pathway." (PMID 40630132, 2025).
iron deficiency (continued). "There are many causes of renal anemia, including insufficient erythropoietin (EPO) production, reduced EPO activity, iron deficiency and other metabolic disorders, malnutrition, inflammatory states, massive blood loss, and more." (PMID 41155680, 2025). "Renal anemia is caused by many factors such as reduced production of erythropoietin (EPO) in the kidneys, reduced red blood cell (RBC) survival, bleeding due to dysfunctional platelets, and profound iron deficiency due to renal failure." (PMID 38345059, 2024). "Iron deficiency is also prevalent in CKD patients due to chronic inflammation, impaired erythropoietin production, and elevated circulating hepcidin levels, which worsen serum iron levels as eGFR decreases." (PMID 39595570, 2024). "Functional iron deficiency in CKD patients is mainly attributed to an increase in hepcidin levels caused by chronic inflammation, decreased renal clearance, and reduced EPO levels." (PMID 37108056, 2023). "This case also highlights the value of serum erythropoietin and RBC count, when PV is suspected and severe iron deficiency is present." (PMID 36779103, 2023). "They include a decrease in endogenous erythropoietin (EPO) production, absolute and/or functional iron deficiency, and inflammation with increased levels of hepcidin." (PMID 36820565, 2023). "In iron deficiency, HIF-2α increases erythropoietin synthesis in the kidney, whereby IRP1 binds HIF-2α 5′IRE and represses protein translation, limiting erythropoietin production, erythropoiesis, and iron consumption." (PMID 36986429, 2023). "This is explained by the physiological response of increased erythropoietin (EPO) which leads to a rapid increase in red cell production in a backdrop of similar nutritional status, hence leading to iron deficiency due to increased demand." (PMID 36879640, 2022). "In particular, the erythropoiesis is compromised by the renal production and release of erythropoietin (EPO) and from iron deficiency." (PMID 35328440, 2022). "The mechanism beyond is complex including decreased erythropoietin (EPO) production, iron deficiency, inflammation, and enhanced hepcidin levels, all of which are involved in the regulation of FGF23 transcription and/or post-translational modification." (PMID 34536161, 2021). "Iron deficiency results in increased concentrations of hypoxia-inducible factor 1α, which stimulates FGF23 transcription through increased EPO production and perhaps also by directly binding to the FGF23 promoter." (PMID 33675347, 2021). "At the initial stage, several conditions directly associated with CKD, such as chronic inflammation and iron deficiency, cause EPO resistance, whereas in the more advanced stage of CKD, both EPO resistance and EPO deficiency develop." (PMID 34830468, 2021). "They include a decrease in endogenous erythropoietin (EPO) production, absolute and/or functional iron deficiency, and inflammation with increased hepcidin levels, among others." (PMID 33842503, 2021). "In this study, we found that markers of iron deficiency, especially lower iron availability (i.e., lower TSAT and higher sTfR), as well as elevated serum EPO, were associated with an increased risk of mortality in community-dwelling individuals." (PMID 31170159, 2019). "Iron deficiency directly stimulates bone production and cleavage of FGF23 as well as via enhanced renal erythropoietin production." (PMID 30816126, 2019). "Hence, in the current study, we investigated whether iron deficiency and EPO influence FGF23 levels, whether iron deficiency and elevated EPO levels are associated with an increased risk of death, and whether such associations could be explained by variation in FGF23 levels." (PMID 31170159, 2019). "Of interest, the positive association between EPO and FGF23 was in part mediated by functional iron deficiency." (PMID 31170159, 2019).
iron deficiency (continued). "Iron deficiency anaemia (IDA), a common complication in many chronic diseases including CKD, is caused by iron and erythropoietin deficiencies and a decreased responsiveness to the actions of erythropoietin." (PMID 30314359, 2018). "In contrast, hepatic Atoh8 and Hamp1 mRNA levels correlated in vivo in mice over a wide range of conditions of altered iron metabolism (iron overload, iron deficiency, hypotransferrinaemia, hypoxia, PHZ, EPO and carboplatin treatment)." (PMID 24236640, 2014). "Bone marrow iron deficiency, inflammation (CRP>40.0 mg/L) and high levels of erythropoietin (epo>1000 u/L), were found in 30.2%, 81.2% and 95.6% of severely anemic children, respectively." (PMID 24339866, 2013). "This occurred even in the absence of systemic iron deficiency and was independent of endogenous erythropoietin levels." (PMID 39301378, 2024). "Some studies conclude that iron alone is sufficient to improve Hb levels in anemic patients with no additional benefit in the use of EPO, particularly in the setting of iron deficiency." (PMID 37624779, 2023). "Other risk factors could contribute to the decrease of Hb, such as iron deficiency, RBC loss, reduced RBC survival, inflammation and resistance to erythropoietin." (PMID 36694151, 2023). "In addition to a relative deficiency of erythropoietin (EPO), iron deficiency (ID), characterized by either absolute or functional ID, constitutes a common contributing factor to renal anemia." (PMID 36698076, 2023). "Despite this, iron deficiency is not routinely monitored, and iron supplementation and erythropoietin are typically discontinued after the transplant." (PMID 35795334, 2022). "Intracellular iron levels and erythropoiesis are tightly linked through a network of hormones and transcription factors such as EPO, ERFE and HIF-2α which boost erythropoietic output during emergency conditions such as hypoxia, iron deficiency or stress erythropoiesis." (PMID 34440444, 2021). "Hyporesponsiveness is defined clinically as a requirement for high doses of EPO to raise blood Hb level in the absence of iron deficiency." (PMID 33920401, 2021). "Of note, EPO impacts on iron delivery for erythroid progenitors by stimulating TFR1 mediated iron uptake, whereas iron deficiency (ID) results in reduced expression of the erythropoietin receptor (EPOR) component SCRIBBLE and thus in reduced in EPO signaling in erythroblasts." (PMID 34835988, 2021). "Therefore, first, pre-existing iron deficiency upregulates the transcription of FGF23 through activated hypoxia-inducible factor 1 alpha and/or erythropoietin production." (PMID 34901334, 2021). "The result is a “functional” iron deficiency, and even with seemingly increased body iron stores, 10–20 % of cases will present with erythropoietin resistance, such as a lack of response to erythropoietin." (PMID 34126941, 2021). "Injection of recombinant human EPO in mice resulted in increased Fgf23 mRNA and cFgf23, but only marginally increased iFgf23, indicating that production and cleavage of FGF23 are directly linked, as observed in inflammation and iron deficiency." (PMID 33716961, 2021). "Shortened RBC age was observed in patients who were receiving maintenance haemodialysis and was associated with iron deficiency, greater haptoglobin consumption, higher ESA requirements, and poor erythropoietin responsiveness, as well as with greater intradialytic fluid extraction." (PMID 32993543, 2020). "Iron deficiency and acute administration of recombinant EPO increased cFGF23, but not iFGF23 serum concentrations in humans." (PMID 32823844, 2020). "We also show that the synthesis of ERFE protein in the spleen of EPO-treated mice is not affected by iron pretreatment, and that iron deficiency posttranscriptionally downregulates TFR2 protein content in the spleen of erythropoietin-treated mice." (PMID 30958854, 2019).
iron deficiency (continued). "The most commonly reported causes of lack of response to EPO treatment are iron deficiency, secondary hyperparathyroidism, chronic inflammatory processes, and malnutrition." (PMID 31412807, 2019). "While iron deficiency is the leading cause of failure to respond to treatment with EPO; it must not be forgotten that active inflammatory or infectious processes can temporarily block the response to iron therapy and, thereby, to EPO." (PMID 31412807, 2019). "Although splenic TFR2 protein content was not influenced by iron overload, iron deficiency partially attenuated the EPO-induced increase in splenic TFR2 protein." (PMID 30958854, 2019). "Iron deficiency appears as the most frequent cause of failure to respond to treatment with EPO; however, it must not be forgotten that active inflammatory or infectious processes can temporarily block the response to iron therapy and therefore, to EPO." (PMID 31412807, 2019). "In contrast to the effect of iron deficiency, EPO treatment did not result in increased cleavage of HFE2, despite an increase in TMPRSS6 protein content." (PMID 26845567, 2016). "It is largely attributed to decreased erythropoietin (EPO) production and iron deficiency." (PMID 26268514, 2015). "The observation that at all ages and in all HIV groups, EPO concentration explained more variability in TfR levels than did serum ferritin concentration suggests that TfR is not primarily an indicator of iron deficiency in this age group." (PMID 16390553, 2006). "Interestingly, NPRL3-KO erythroblasts failed to appropriately regulate pS6 in response to iron deficiency and EPO deprivation (separately, in replete amino acid conditions)." (PMID 40128524, 2025). "Finally, IV iron tended to suppress circulating erythropoietin levels in ID, but not IR, participants, implying that iron deficiency acts directly to augment erythropoietin expression, as the suppression occurred prior to any increase in Hb concentration." (PMID 35046429, 2022). "The reasons for erythropoietin hyporesponsiveness other than inadequate erythropoietin production are still not known but several factors could be involved, such as iron deficiency, inflammation, hyperparathyroidism or bone marrow dysfunction." (PMID 34895154, 2021). "Blood hemoglobin and hematocrit levels and biomarkers of erythroid demand (i.e., bone marrow erythroferrone and renal erythropoietin mRNA expression) were also unaltered, indicating that Dmt1 siRNA treatment did not cause iron deficiency or decrease iron delivery to the erythron." (PMID 34063414, 2021). "Whether or not they are treated with recombinant human erythropoietin (EPO), patients with absolute iron deficiency should be treated with iron supplements." (PMID 34629085, 2021). "EPO therapy seems a viable treatment option to optimize peri-operative Hb levels and to achieve effective cessation of blood transfusion in patients with a low pre-operative Hb concentration without iron deficiency." (PMID 31468111, 2020). "There is relatively little information on Hamp gene expression in mice subjected both to EPO treatment and iron deficiency; in particular, it is not established to what extent the administration of EPO will influence the already low Hamp mRNA content in iron-deficient mice." (PMID 30958854, 2019). "EPO-induced splenic Tfr2 mRNA content was not influenced by iron deficiency." (PMID 30958854, 2019). "It provides new data on the induction of splenic ERFE and TFR2 by EPO, suggesting that the induced levels of these proteins are not further posttranscriptionally regulated by iron overload, but that the EPO-induced splenic TFR2 protein levels are decreased by iron deficiency." (PMID 30958854, 2019).
iron deficiency (continued). "The associations we observed between functional iron deficiency, high EPO levels, and mortality led us to explore FGF23 as a potential downstream factor mediating these associations, given accumulating evidence supporting a direct relationship between iron status, EPO, and FGF23 metabolism." (PMID 31170159, 2019). "Although the levels of endogenous erythropoietin significantly decreased during correction of iron deficiency, the same response was observed in those with and without thrombocytosis, indicating that erythropoietin is not the principal regulator of thrombocytosis." (PMID 25038614, 2014). "In line with previous results, in patients without acute inflammation and severe iron deficiency the “high hepcidin” 736 V TMPRSS6 variant was associated with higher erythropoietin maintenance dose (p = 0.016), independently of subclinical inflammation (p = 0.02)." (PMID 23433094, 2013). "In a previous study among liver transplant recipients, erythropoietin production and hematocrit levels were significantly reduced in CNI users, however the association with iron deficiency was not investigated." (PMID 31484461, 2019).